KRAS (KRas proto-oncogene, GTPase)
Diseases named in the same sentence as KRAS in open-access papers (continued):
Sharing a sentence is not in itself a finding about the gene and the disease.
lung cancer (continued). "STK11 and KEAP1 co-mutations with KRAS are primarily observed in lung cancer, as these two genes are rarely mutated in other cancers with high KRAS mutation rates." (PMID 40611261, 2025). "In recent years, research on radiomics-based prediction of KRAS mutations in lung cancer has surged." (PMID 41584578, 2025). "In lung cancer, KRAS mutations alongside loss of the tumor suppressor gene LKB1 are significantly correlated with m6A modifications, particularly affecting AlkB family member 5 (ALKBH5) levels." (PMID 39806421, 2025). "The recently developed pan-KRAS inhibitor daraxonrasib, also known as RMC-6236, is capable of targeting a wide array of KRAS mutations and shows promise against pancreatic and lung cancers." (PMID 40779492, 2025). "KRAS G12C (41%), KRAS G12V (22%), KRAS G12D (12%), and KRAS G12A (9.3%) represent the most commonly observed mutations in KRAS within lung cancers." (PMID 39960727, 2025). "Patients with KRAS mutant lung cancers frequently present with co-mutations in the KEAP1-NRF2 pathway, which results in the constitutive activation of the transcription factor NRF2 within the tumour cells." (PMID 40890297, 2025). "In lung adenocarcinomas, KRAS mutations also occur (about 20–30%, often in smokers), but the most frequent subtype in lung cancer is G12C." (PMID 41310725, 2025). "Mutations in KRAS contribute to ~25% of lung adenocarcinomas (LUADs), the most frequent lung cancer subtype." (PMID 41219537, 2025). "These proof of principle and mechanism studies demonstrate in a relevant lung cancer model a significant susceptibility of KRAS mutant/STK11 deficient lung adenocarcinoma to dual mTORC1/2 inhibition." (PMID 40069402, 2025). "Among these mutations, KRAS G12C inhibitors, such as adagrasib and sotorasib, have presented certain clinical efficacy in the treatment of KRAS G12C-mutated lung cancer." (PMID 40568576, 2025). "Despite these advances, surprisingly little is known about the molecular mechanisms linking KRAS mutations to lung cancer." (PMID 41219537, 2025). "Mutations in the KRAS gene are well-known tumourigenic drivers of colorectal, pancreatic and lung cancers." (PMID 39820726, 2025). "The Food and Drug Administration has approved two KRAS G12C inhibitors-sotorasib and adagrasib—as treatment options for KRAS G12C-mutated nonsmall-cell lung cancer." (PMID 40740763, 2025). "Among them, KRAS mutations are particularly common in several cancers such as pancreatic, colorectal, and lung cancers." (PMID 39806421, 2025). "In summary, these KRAS G12C-mutated lung cancer cell lines exhibited marked sensitivity to the combination of sotorasib and adavosertib, demonstrating a strong synergistic effect." (PMID 40885709, 2025). "Despite strong preclinical rationale supporting the use of mTORC1/2 inhibition in STK11-deficient lung cancer, clinical activity of vistusertib was clearly disappointing, even in cancers with concomitant KRAS mutations." (PMID 40069402, 2025). "In our study, we also found that ACACA expression is related to mutations of common driver genes in NSCLC, which agrees with recent research that common driver gene mutations in lung cancer, such as KRAS, EGFR, ROS1 and ALK, are closely related to metabolism." (PMID 41169354, 2025). "Sotorasib and Adagrasib have demonstrated efficacy in prolonging survival and improving safety profiles among patients with KRAS-mutated lung cancer." (PMID 41584578, 2025). "Another important gene implicated in radon-induced lung cancer is KRAS, an oncogene that, when mutated, leads to uncontrolled cell proliferation." (PMID 40427695, 2025).
lung cancer (continued). "In KRAS-mutated lung cancer, high expression of DRP1 regulated lactate utilization and redox homeostasis, providing support for tumor cell survival and proliferation." (PMID 40166469, 2025). "In fact, our preliminary data has shown effectiveness of the ADC in lung cancer cell lines with KRAS mutations and that express proTGFα." (PMID 40410803, 2025). "KRAS is a common mutation in colorectal (prevalence ∼40%), but also in pancreatic (prevalence ∼70%) and lung cancers (prevalence ∼20%)." (PMID 39851266, 2025). "NSCLC accounts for approximately 85% of lung cancers, and Kirsten rat sarcoma (KRAS) is the most commonly mutated gene in NSCLC." (PMID 41394615, 2025). "Another study reported that targeted therapies including specific inhibitors targeting KRAS G12C mutation induced MIG6 loss in different lung cancer cell lines." (PMID 39948411, 2025). "Professor Rafael Rosell from the Catalan Institute of Oncology in Spain stands out for his work on KRAS mutation-associated lung cancer and is among the leading contributors in this research area." (PMID 41293265, 2025). "Background/Objectives: Several genetic alterations have been identified as drivers of uncontrolled cell growth in lung cancer, with KRAS mutations representing the most prevalent driver oncogene." (PMID 41463229, 2025). "Missense mutations in the 12th codon of KRAS are key drivers of lung cancer, with glycine-to-cysteine (G12C) and glycine-to-aspartic acid (G12D) substitutions being among the most prevalent." (PMID 40890128, 2025). "These mutant-specific KRAS-targeted drugs, including Sotorasib, Adagrasib, and MRTX1133, provide new hope for patients suffering from highly malignant tumors driven by KRAS mutations such as pancreatic cancer, lung cancer, and colon cancer." (PMID 41391757, 2025). "KRAS-mutant lung cancers display a particularly broad co-mutation profile, reflecting their frequent origin in smokers with attendant mutational damage." (PMID 40723270, 2025). "Among these, KRAS G12C is the most common variant, accounting for about 40% of KRAS mutations in lung cancer." (PMID 39941723, 2025). "Being the most common KRAS subvariant in non–small cell lung cancer, KRAS G12C became the first targetable mutation with two FDA-approved drugs—sotorasib and adagrasib." (PMID 40970755, 2025). "Recent findings in a KRAS-driven lung cancer model suggest that loss of N-myristoylation is particularly catastrophic when certain mitochondrial import factors TIM17 A are high, whereas cells without that dependency cope better." (PMID 40335986, 2025). "Lung cancer treatment and prognosis is highly dependent on molecular subtype, and KRAS mutations are the most common genetic driver." (PMID 40715535, 2025). "Overall, the significant links between chemotherapy, radiation, and KRAS mutations align with the biological behavior of KRAS-mutant lung cancer, underlining the necessity for alternative treatments like chemotherapy and radiation in these patients." (PMID 40502411, 2025). "In chemotherapy resistant lung cancer, presence of M2 macrophages correlated with KRAS mutation and poor survival." (PMID 40524071, 2025). "The same analysis reported the common features of the associated lung cancer, including the adenocarcinoma pathology and at least one driver mutation in nearly half of the cases, including KRAS, EGFR, ALK, BRAF, and ATM." (PMID 41476748, 2025). "KRAS mutations resulting in constitutive activation are commonly found in pancreatic, colorectal, and lung cancers." (PMID 41322195, 2025). "The patient had KRAS G12C-mutated lung cancer and was treated with sotorasib, a selective KRAS G12C inhibitor approved for second-line treatment of lung cancer." (PMID 40277845, 2025). "Sotorasib and adagrasib, the most clinically advanced KRAS G12C inhibitors, have received FDA approval for the treatment of KRAS G12C-mutated lung cancer." (PMID 41303394, 2025).
lung cancer (continued). "Correspondingly, Western blot analysis revealed high levels of REGγ expression in human lung cancer cells harboring KRAS mutations." (PMID 40091835, 2025). "To further explore the molecular mechanism underlying KRAS-mutant–mediated platinum resistance in lung cancer, we performed RNA-Seq analysis in control and KRAS G12V–expressing NCI-H522 cells." (PMID 39960727, 2025). "Here we show that in LKB1-deficient KRAS-mutant lung cancer cells, inhibition of KRAS or its downstream effector MEK leads to hyperactivation of JNK due to loss of NUAK-mediated PP1B phosphatase activity." (PMID 40316540, 2025). "In a case series involving two lung cancer patients, CSF analysis of KRAS mutations aided in the early detection of leptomeningeal metastasis." (PMID 40362343, 2025). "We propose that sequence-encoded structural distortion, rather than lesion chemistry alone, dictates lesion recognisability, binding pathway success, and ultimately mutational hotspot formation within KRAS in smoking-related lung cancers." (PMID 40970185, 2025). "In lung cancer, KRAS G12C was the second most frequent mutation (18.6%), whereas in pancreatic cancer, G12C accounted for only 2.0% of all KRAS mutations." (PMID 40970755, 2025). "In this challenging subset of KRAS-driven lung cancers, the loss of LKB1 leads to a profound immunosuppressive TME characterized by diminished immune cell infiltration and reduced sensitivity to ICIs." (PMID 41283988, 2025). "In lung adenocarcinoma patient samples and KRAS-driven lung cancer mouse models, KRAS mutations engage PI3K/STAT3 axis activation to suppress miR-34a, resulting in transcriptional depression of the “don’t eat me” signal CD47." (PMID 40303413, 2025). "In lung cancers, KRAS mutations affect roughly 25% of non-small cell lung cancers, with codon 12 mutations predominant." (PMID 41514544, 2025). "Kirsten rat sarcoma (KRAS) mutations (KRASms) are the most common lung cancer mutations, affecting 25% of NSCLC cases." (PMID 41395604, 2025). "Within these KRAS mutations, the G12C variant (responsible for ~40% of KRAS mutations in lung cancer) made up ~28.1%." (PMID 40244261, 2025). "Using this approach, a panel of murine lung cancer cell lines has been developed that expresses the major drivers of human LUAD: KRAS (both G12D and G12C mutants), EGFR mutations, EML4-ALK fusions, and RET fusions." (PMID 40805126, 2025). "KRAS mutations are key oncogenic drivers in lung cancer, yet effective pharmacological targeting has remained a major challenge due to the protein's elusive and dynamic binding pockets." (PMID 41333851, 2025). "A novel PEG-PLE/C14-PEI nanoplex formulation for delivering Cas9 mRNA and sgRNA, targeting KRAS G12S mutations in lung cancer cells demonstrates high gene-editing efficiency and significantly enhanced cancer cell apoptosis and migration inhibition." (PMID 39687993, 2025). "Despite the widespread occurrence of KRAS constitutively active mutations in lung cancers, the association between these mutations and platinum resistance in NSCLC has not been fully investigated." (PMID 39960727, 2025). "Mutations of the Kirsten rat sarcoma viral oncogene homolog (KRAS) are most frequently observed among lung cancer patients with smoking history." (PMID 40437549, 2025). "We utilized six KRAS G12C-mutated lung cancer cell lines in our study: H2122, H23, H358, H2030, Calu-1, and SW1573." (PMID 40885709, 2025). "CRISPR-Cas9 has emerged as a highly effective and customizable tool for genome editing, holding promise for the treatment of KRAS mutations in lung cancer, however, developing an efficient and bio-safe material is a key barrier." (PMID 39838780, 2025). "Lung cancer adenocarcinomas are predominantly associated with the following: Kirsten rat sarcoma viral oncogene homolog (KRAS - 32%); epidermal grow factor receptor (11%), and V-Raf murine sarcoma viral oncogene homolog B (BRAF - 7%) driver mutations." (PMID 39955067, 2025).
lung cancer (continued). "In contrast, KRAS mutations are strongly associated with aggressive malignancies, occurring in 91% of pancreatic, 42% of colon, and 33% of lung cancers." (PMID 40906088, 2025). "In this study, we introduce C14-PEI as a micelleplex system capable of efficiently co-delivering Cas9 mRNA and sgRNA to excise mutated KRAS alleles in lung cancer cells." (PMID 39838780, 2025). "Single-agent KRAS G12C inhibitors (sotorasib and adagrasib) have shown improved outcomes in patients with non–small-cell lung cancer with KRAS G12C mutation but limited activity in CRC patients." (PMID 39941081, 2025). "KRAS-mutated lung carcinoma has recently gained importance since the introduction of specific therapies targeting G12C mutations." (PMID 40423070, 2025). "Yet, in recent years, a growing number of small molecules, such as the GTPase inhibitors, has been investigated in clinical trials of lung cancer patients harboring KRAS mutations, yielding promising results with improved outcomes." (PMID 38846975, 2024). "In contrast, both CD47 expression and MHC class I expression was significantly lower in lung cancers with KRAS driver mutations." (PMID 38483480, 2024). "Mutations in the KRAS gene are among the most common genetic alterations in lung cancers, particularly in NSCLC." (PMID 39199653, 2024). "KRAS mutation occurs in 25% of all lung cancers and the concomitant mutations in LKB1 determine aggressive subtypes of these tumors." (PMID 39763604, 2024). "It is another unique feature of mutant KRAS that the G12C variant in lung cancer is the major oncogenic driver, while in other tumors, mutant KRAS (which is either G12D or G12V) is a minidriver cooperating with other driver oncogenes." (PMID 38473821, 2024). "The mutational spectrum of KRAS is particularly diverse, but the most frequent mutation in lung cancer is G12C." (PMID 39763604, 2024). "The predominant site for mutation in KRAS in lung cancer is glycine 12, and all KRAS-mutant tumors in our cohort were mutated at that site." (PMID 39052387, 2024). "Selective KRAS inhibitors, such as sotorasib, are effective against KRAS G12C mutation-positive lung cancer." (PMID 38466521, 2024). "Concomitantly with these main targeted therapies, there are others that have already been approved by the FDA for lung cancer treatment targeting KRAS (G12C mutation), MET (exon 14 skipping), NTRK, HER2, and RET fusion." (PMID 38793028, 2024). "EGFR mutations are found in approximately 50% of cases recorded in Asian populations, whereas KRAS mutations predominate in Caucasian lung cancer populations with a frequency of 30–35%." (PMID 38313018, 2024). "By utilizing KRAS-mutated lung cancer cells and organoids, researchers demonstrated MA's ability to inhibit proliferation and induce endoplasmic reticulum (ER) stress via a ROS-dependent mechanism." (PMID 39104501, 2024). "The persistence of a wild-type KRAS allele in multiple KRAS-mutated lung cancer cell lines was observed in preclinical studies." (PMID 39301544, 2024). "Every year, about 50,000 people in the United States alone receive a new diagnosis of lung cancer caused by KRAS mutations." (PMID 38528576, 2024). "A study in which WES of primary lung–BrM pairs was carried out showed that BrMs exhibited higher somatic variants and chromosomal alterations than primary lung cancers, particularly in genes associated with lung cancer (e.g., KRAS, ROS1, and STK11)." (PMID 39593114, 2024). "In the context of lung cancer, MA-induced ER stress not only sensitizes KRAS-mutated cells to osimertinib but also disrupts mitochondrial function, leading to lipid peroxidation and ultimately ferroptosis." (PMID 39104501, 2024). "The loss of GRP78 induces UPR and apoptotic markers, which are associated with the loss of cell viability in lung cancer cell lines carrying the same KRAS mutation." (PMID 38734764, 2024).
lung cancer (continued). "In patients with lung cancer, we demonstrate that KRAS mutations increase tumor immunogenicity; however, KRAS/STK11 co-mutated patients display an immune-excluded phenotype." (PMID 39113608, 2024). "Within the spectrum of genetic changes in cancer, mutations in KRAS hold prominence, particularly in pancreatic, colorectal, and lung cancers." (PMID 39431199, 2024). "The frequency of KRAS mutations varies across cancer types, being particularly high in pancreatic, colorectal, and lung cancers." (PMID 39202410, 2024). "The frequency of co-mutations of KEAP1 and KRAS in lung cancers, which further increases treatment resistance and decreases survival, adds to the importance of addressing the biologic complexity and immune regulation by these tumors." (PMID 38542481, 2024). "As many as 30% of the patients with non–small cell lung cancer harbor oncogenic KRAS mutations, which leads to extensive remodeling of the tumor immune microenvironment." (PMID 39113608, 2024). "It would be of great interest to transfect cells not only transiently but stably to investigate the long-term effects of KD in lung cancer patients with KRAS mutations." (PMID 39201772, 2024). "Regarding MTHFD1, besides its connection with survival outcomes in lung cancer patients with WT KRAS, its high expression was also associated to poorer survival in patients with KRAS/LKB1 co-mutations." (PMID 38997257, 2024). "Our results suggest that ERK5 inhibitors prevent resistance to FAK inhibitors and are expected to provide a good therapeutic strategy for lung cancer patients with KRAS mutations." (PMID 39271958, 2024). "Mutated KRAS activation is a primary cause of lung cancer deaths with inadequate knowledge of its downstream targets and growth mechanisms of tumor cells." (PMID 38791400, 2024). "In vitro experiments on KRAS-mutated lung cancer cells revealed that luteolin inhibited cell growth and induced apoptosis at minimal concentrations." (PMID 39690423, 2024). "The significance of the KRAS gene in lung cancer has been extensively studied, and mutations in this gene are frequently associated with smoking." (PMID 38828424, 2024). "Our bioluminescence imaging results showed that loss of HOXC10 significantly decreased bone metastasis in KRAS-mutant lung cancer." (PMID 39191757, 2024). "We found that critical driver alterations, including canonical EGFR and KRAS mutations, were detected across the spectrum of lung cancer precursors." (PMID 38798564, 2024). "Loss of LKB1 in KRAS mutant lung cancer cells leads to YAP-mediated transcriptional activation, through regulation of localization of SCRIB, a scaffold protein involved in cell polarization, and Hippo kinases MST and LATS activity." (PMID 39544365, 2024). "This is particularly good news for the treatment of lung cancer, where G12C is the most common KRAS subtype and accounts for about half of all KRAS mutation types." (PMID 39457426, 2024). "As one of the most common genetic alterations, KRAS mutations play a pivotal role in the growth of lung cancer, particularly non-small cell lung cancer." (PMID 39594840, 2024). "In summary, luteolin and apigenin both significantly reduced the growth of lung cancer associated with KRAS mutants and downregulated the expression of PD-L1 induced by IFN-γ." (PMID 39690423, 2024).